CD44 (CD44 molecule (IN blood group))
Diseases named in the same sentence as CD44 in open-access papers (continued):
Sharing a sentence is not in itself a finding about the gene and the disease.
tumor (continued). "Furthermore, to assess whether changes in T‐cell levels in TME of Cx3cr1‐Rheb1Δ/Δ tumours were due to infiltration and/or proliferation, we examined the expression of Ki67 and of adhesion molecules CD44 and CD62L." (PMID 32567735, 2020). "The impact of fibroblasts became stronger at higher densities, i.e., a CD44+ LS1034 fraction of about 10% was observed after 4 days of co-culturing when (1.2-1.3)×104 fibroblasts per cm2 culture surface were seeded 24 h prior to the addition of the same number of tumor cells." (PMID 32685007, 2020). "Other studies have shown that CD44 expressions in non-tumor tissues may predict HCC recurrence." (PMID 32210805, 2020). "CD44 has been shown to be involved in lymphocyte activation and homing, which could corroborate the increased infiltration of immune cells in the recurrent tumor samples in this study, although more information on the exact function of CD44 is needed before conclusions can be made." (PMID 33352957, 2020). "In summary, we found that IR with the PTV95 program (a higher radiotherapy dose) resulted in increased radioresistance than IR with the Non‐PTV95 program (a lower radiotherapy dose), and the tumor microenvironment (CD44 level) may enhance radioresistance in IR with the Non‐PTV95 program." (PMID 31746135, 2020). "Furthermore, exosomes may act as mediators of OC cell-mesothelial cell communication, since CD44 has been shown to be transferred through exosomes to mesothelial cells, inducing the expression of factors that favor tumor cell invasion." (PMID 32512891, 2020). "Interestingly, A6, a peptide sharing sequence homology with HA binding domain of CD44, strongly enhanced the adherence of CD44-expressing cancer cells to HA, and effectively suppressed tumor cell migration in vitro and tumor metastasis in xenografted B16-F10 mouse model." (PMID 31898491, 2020). "Thus, CD44 KO within MDA-MB-231 cells decreased tumor cell colonization within the lungs." (PMID 32455980, 2020). "The binding of HA to CD44 induces conformational changes to the receptor as well as post-translational modifications that regulate downstream signalling pathways, resulting in numerous pathobiological processes, including inflammation, wound healing, tumour growth, and metastasis." (PMID 32517712, 2020). "However, since HA can be tumor preventing or promoting, further studies are needed to determine whether HA being produced by the CD44 KO cells may have tumor suppressive properties." (PMID 32455980, 2020). "This delivery nanoparticle could target tumor-specific CD44 molecule." (PMID 33303029, 2020). "Though the majority of CD44v6-regulated miRNA have predicted mRNA targets engaged in tumor progression, the mRNA analyses pointed towards a contribution by additional regulators, one of which could be lncRNA, links between CD44 and lncRNA in gastrointestinal cancer being described." (PMID 31485223, 2019). "Moreover, when mice were pre-administered with a dose of free HA to saturate CD44 receptors, the fluorescence signal in the tumour significantly weakened compared to that of unsaturated receptors, demonstrating the role of HA in active targeting through CD44-mediated endocytosis." (PMID 31311176, 2019). "Practically, the fluorescence density was negligible in tumor tissues as compared to that of liver, which indicates that nanophotosensitizers efficiently targeted the CD44 receptor of tumor cells and their delivery capacity can be controlled by CD44 recognition." (PMID 31546620, 2019). "In addition, TGFβ is suggested to increase the expression of the HA receptor CD44 in tumor cells." (PMID 31361756, 2019). "Thus, different cells of a tumor can express various, and possibly different sets of CD44 isoforms." (PMID 31139149, 2019). "However, a study from China showed that CD44 rs187115 polymorphism was associated with a decreased risk for non-small cell lung cancer (NSCLC), but was also significantly related with bone metastasis and tumor stage for NSCLC patients." (PMID 31682231, 2019).
tumor (continued). "Indeed, numerous studies have indicated that alternative splicing occurs frequently in cancer cells, and a plethora of cancer-specific splice variants have been reported; and some of them are considered to be candidate cancer biomarkers, such as CD44 and the Wilms tumor (WT1) genes." (PMID 31440421, 2019). "Importantly, to demonstrate the critical role of SNAIL in driving the Mes/CSC phenotype, we expressed exogenous SNAIL in Ep/non-CSC and confirmed that it induced Mes/CSC properties, as demonstrated by repressed E-cadherin expression, increased CD44 expression, and facilitated tumor sphere formation." (PMID 31036052, 2019). "In addition, CD44+ cells possess a distinctive genetic profile regarding tumorigenicity, chemoresistance, constitutive NFκB activity, and has the potential to promote a pro-inflammatory tumor microenvironment." (PMID 31277278, 2019). "Interestingly, sustained IFN-β treatment (100 IU/mL every 48 h up to 3 weeks) repressed SNAIL-mediated CSC properties including partial reversion of CD44 expression and repressed tumor sphere formation along with partial repression of steady-state SNAIL protein." (PMID 31036052, 2019). "Moreover, higher nuclear SHCBP1 was detected in NSCLC cells cultured in serum-free medium than in serum-containing medium, as well as in CD44/ EpCAM double-positive cells compared to the corresponding parental tumor cells, suggesting an important role of nuclear SHCBP1 in CSCs regulation." (PMID 30177836, 2019). "Thus, our data show that FTD treatment is effective against CSC-like cells and might be applied as CSC-targeting chemotherapy for tumor subtypes with high CD44 and CD133 expression." (PMID 31619711, 2019). "We believe that this new information could establish the ground work for developing novel therapeutic agents that would effectively target HA/CD44-activated signaling events and specific downstream target molecules/functions in tumor cells-thus providing important new cancer therapies." (PMID 31293964, 2019). "The knowledge obtained from this biogenesis study of miR-21 regulated by Nanog-DROSHA-p68 complexes may provide useful foundation for designing new drug target to downregulate miR-21 and increase tumor cell death and enhance chemosensitivity for the treatment of HA/CD44-mediated cancer." (PMID 31293964, 2019). "Similarly, CD44+/24− A549 population isolated by magnetic separation (MACS) was assayed for their in vivo tumor initiation ability compared to their parental un-sorted A549 by subcutaneous injection into the flanks of Nod/SCID immunocompromised mice at the indicated concentrations." (PMID 31796785, 2019). "In addition, 71.4% of the HCC patients demonstrated CTCs positive for cancer stem cell marker, CD44, suggesting that the major population of CTCs could possess stemness properties to facilitate tumor cell survival and dissemination." (PMID 31819089, 2019). "Furthermore, the HA-ss-PLGA can target CD44-expressing tumor cells." (PMID 31311150, 2019). "Emergence of certain myeloid subsets in the spleen, such as CD44+MDSCs and IL-17A+MDSC were associated with advanced cancer, while within the lymphoid subsets, the absence the B220+ B-cells, CD62L+ B-cells, CD62L+CD4+ T-cells, and CD62L+ CD8+ T-cells was shown in the untreated tumor bearing mice." (PMID 31881770, 2019). "Also, we found that hRAT-CMs increase CD44 expression in some tumor cell lines." (PMID 31534630, 2019). "Instead, it could reflect increased retention due to higher CD69 expression and possibly increased frequency of central memory CD44+ CD27+ T cells at the tumor site which are known to be more efficacious in mouse models of ACT, as found in the disseminated tumor model." (PMID 31249570, 2019). "These include increased shift toward M2 protumoral phenotype in tumor-associated macrophages, a reduced granzyme B-producing CD3+CD8+GzmB+ T cells, increased circulating VEGF and increased cancer stem cells markers on Oct4+ and CD44+CD133+ expressing TC1 tumor cells." (PMID 30811514, 2019).
tumor (continued). "Interestingly, in Ep/non-CSC transduced to express constitutive SNAIL, we found that sustained IFNβ treatment repressed SNAIL-mediated CSC properties (partial reversion of CD44 and repressed tumor sphere initiation capacity) while partially reducing steady-state levels of SNAIL protein." (PMID 31036052, 2019). "Moreover, a high level of CD44 showed a possible correlation with poor differentiation (ORTotal CD44 isoforms = 1.44, 95% CI = 1.00-2.08, P = 0.051), elevated level of CD44v6 tend to be correlated with tumor size (OR = 1.71, 95% CI = 0.99-2.96, P = 0.056)." (PMID 31114754, 2019). "Additionally, CD44 was highly expressed in tumor endothelial cells compared to normal tissue." (PMID 29890852, 2018). "Additionally, they indicate that Roy-Bz may also target drug-resistant CSCs, preventing tumor dissemination and recurrence, as evidenced by the pronounced reduction of colonosphere growth and formation, and by the depletion of the CD44 stemness marker." (PMID 29348560, 2018). "It remains unknown if there exists a relationship between CD44 expression and various tumor stages." (PMID 30121075, 2018). "The close interactions between CD44 and its selected binding partners play a pivotal role in coordinating “cross-talk” among various intracellular signaling pathways leading to the concomitant onset of multiple functions such as tumor cell proliferation and invasion." (PMID 30165890, 2018). "However, it has not been shown that a specific CD44 variant isoform is associated with a certain tumor type." (PMID 29577645, 2018). "In addition, the established role of CD44 in maintaining stemness and the function of cancer stem cells in tumor regeneration following therapy suggests that CD44 may also be an important prognostic marker." (PMID 29747682, 2018). "To further determine whether calcitriol treatment affects the CSC population in the tumor, we isolated the xenograft tumor cells after completion of calcitriol treatment, and analyzed the percentage of CD44+CD117+ cells, which have been validated to possess CSC properties." (PMID 29581858, 2018). "Attempts to isolate BCSCs based on the basal cell surface marker CD44 expression-despite being closely associated with tumor progression and aggressiveness- showed substantial variation among basal tumor subtypes and have been at least unsuccessful in non-muscle-invasive tumors." (PMID 30072631, 2018). "However, it should be pointed out, HA is not internalised in all CD44 expressing cell types: therefore, tumours that highly express CD44 may take up only a little amount of HA." (PMID 29670009, 2018). "Dysregulation of cell stemness phenotype (e.g., β‐catenin and CD133), cell–cell interaction (e.g., CD44 and E‐cadherin), and cell–matrix interaction (e.g., matrix metalloproteinase) as well as of inflammation (e.g., cytotoxic T cells) are essentially involved in tumor budding." (PMID 30069738, 2018). "Thus, it was shown that the CD44+/c-kit+ population had an approximately 5000-fold increase in tumorigenicity, with tumors forming after the inoculation of as few as 100 cells from primary tumor, xenograft or in vitro-grown spheroid cell population." (PMID 29389895, 2018). "Furthermore, the role of CD44 in tumor angiogenesis is enhanced by its binding to immobilized HA." (PMID 28326306, 2017). "Single nucleotide variants were analyzed and a total of 51 somatic variants were identified in tumor and EPCAM+CD44+CD49f+ samples compared to total lymph nodes, and of these we identified 20 synonymous variants, 26 non-synonymous variants, 3 insertion-deletions, and 2 unknown variants." (PMID 28487492, 2017).
tumor (continued). "CD44 has multifunction in cancer cells, like acts as a specific receptor for promoting migration, interacts with osteopontin and regulates its cellular functions leading to tumor progression, monitors the extracellular changes and is vital in regulating cell survival, migration and differentiation." (PMID 28076853, 2017). "Therefore, it is conceivable that CD44-dependent expression of cell surface CD146 may have dual functions at different stages of BC tumor development that are most likely dependent on the tumor microenvironment." (PMID 29121955, 2017). "In summary, our findings imply that the tumor microenvironment and gene regulatory networks could generate phenotypic diversity, including cells defined by a CD44+/CD24− state, enabling the development of novel, heritable genotypic profiles that could be selected for." (PMID 28092266, 2017). "According to MS data, we have compared, in relation to the expression of Co-029, the contribution of EGFR, a major RTK signaling molecule, and CD44 that are both involved in tumor cell motility, to determine how their modulation may influence this cellular function." (PMID 28418857, 2017). "Therefore, our studies demonstrate that CD13+CD44+ SCs may represent a subset of LCSCs and display the capacity for promoting tumor growth, invasion and metastasis." (PMID 28199981, 2017). "Therefore, the decrease in CD44+ CSCs in invasive GL261 tumors in p65 KO mice compared to controls could be the result of the anti-tumor effect of CD8+T cells in syngeneic GBM model." (PMID 29062041, 2017). "Moreover, potential crosstalk between serglycin and CD44, may function as an amplifier modulating a variety of tumor induction signals." (PMID 28445977, 2017). "Results from hierarchy clustering and linear regression analyses showed that the expression of tumor-associated ASC and IL-18 are closer to ALDH1 expression, NLRP3 and Caspase-1 are close to ALDH1 expression, and NLRP3, Caspase-1, ASC, and IL-18 are close to CD44 and BMI1 expression." (PMID 28865486, 2017). "Expression of Oct4 in the CD44-positive tumor cells could also be detected, albeit in a small percentage, in the tissue slices of cisplatin-resistant TCCSUP tumor xenografts after cisplatin treatment, suggesting a potential role for Oct4 in the poor response of tumors to cisplatin treatment." (PMID 27244887, 2017). "Moreover, as few as 103 CD44+/CD24−/low cells were sufficient to drive tumor formation." (PMID 28212529, 2017). "However, trastuzumab treatment caused elevated CD44 expression on tumor cells that metastasized into the lung and liver but did not hinder tumor cell dissemination into the bone marrow." (PMID 27835865, 2017). "Therefore, a CD44-targeted therapeutic approach could be utilised for better anti-tumour drug delivery." (PMID 27825361, 2016). "Moreover, CD44 expression correlated with less aggressive tumor behavior, though the association with survival was not statistically significant." (PMID 27285762, 2016). "It indicated that CD44 expression may regulate anti-tumor immunity by suppressing CD4 expression." (PMID 27323782, 2016). "To confirm that CD44+ cells may be enriched for CSCs, we performed tumor sphere formation assay." (PMID 27833077, 2016). "In addition to enriching the tumor cell population with CD44+/β1+ cells (as we previously published), TME Stimulation selected for CD44+/CD24low/− stem-like cells, that were further enriched by doxorubicin treatment and demonstrated high plasticity in vitro and in vivo." (PMID 27835603, 2016). "A challenge to developing therapies against CD44 lies in the fact that CD44 represents a large family of variant isoforms expressed through alternative splicing of the CD44 gene and controversy exists as to which isoforms are tumor-protective and which may act to promote tumor progression." (PMID 27379207, 2016).
tumor (continued). "Therefore, it indicates that grifolin may impede metastatic tumor cells adhesion and migration through inhibition of CD44 and MMP2 expression and function as well." (PMID 27626695, 2016). "Hence, CD44 may be involved in several malignant biological processes, such as tumour initiation, development, and metastasis." (PMID 26839535, 2016). "Since gal-3 increases the endocytosis of MUC1, integrin β1 and CD44, high levels of sTn on the tumor cell surface might be a mechanism to block gal-3-mediated endocytosis, thus increasing the stability of anti-apoptotic molecules and therefore, chemotherapy resistance." (PMID 27835877, 2016). "In addition, we also found enhanced EMT (increased N-Cadherin and reduced E-Cadherin) and CSC phenotypes (CD44 and Oct-4) in the PC-3RR xenograft tumors compared to the PC-3 control tumor, which is consistent with our previous in vitro studies with CaP-RR cell lines." (PMID 27708237, 2016). "The tumorigenic subpopulation could be serially passaged, and the tumor formed in each time of passage contained mixed population of additional CD44+CD24−/low lineage− tumorigenic cells as well as the phenotypically diverse mixed populations of nontumorigenic cells present in the original tumor." (PMID 27200096, 2016). "Since CD44-standard form did not generate the same immunological response against tumors, it suggested that CD44 variant (v3–10) and not CD44s was functional in promoting tumor growth and metastasis in DA3 cells." (PMID 25954275, 2015). "Moreover, CD44 participates in homing and engraftment of various tumor cells." (PMID 25941526, 2015). "Therefore, CD90+/CD44+ cells may also serve as a sensitive and specific marker for early tumor diagnosis in HCC." (PMID 26097877, 2015). "Interestingly, the mesenchymal tumor cells with a CD44+/CD24−/low phenotype could re-establish an epithelial tumor and exhibit drug resistance, which resembled the characteristics of breast CSCs." (PMID 25686831, 2015). "Our results also demonstrate that quiescent CD44 on normal cells could be activated in tumor microenvironments, providing additional evidence for the specific active state of CD44 on tumor cells." (PMID 25909172, 2015). "CS chains of serglycin are mainly responsible for binding to CD44 and collagen type I. Serglycin binding to CD44 most likely mediates the cell surface localization of serglycin that further interacts with matrix collagen type I thus promoting the adhesion of tumor cells." (PMID 26581653, 2015). "In addition, CD44 is a well-described tumor stemness marker." (PMID 26189059, 2015). "Moreover, both TrkA tyrosine kinase inhibition with lestaurtinib and CD44 silencing with siRNA inhibited cell growth in vitro as well as tumor development in mouse xenograft model; combined treatment significantly enhanced the antineoplastic effects of either treatment alone." (PMID 25840418, 2015). "As the formation of TrkA/CD44 complex was independent of TrkA phosphorylation, and TrkA tyrosine inhibitor K252a allowed for sustained TrkA and CD44 association at the plasma membrane, we wanted to know if combinational targeting of TrkA and CD44 could more efficiently inhibit tumor cell growth." (PMID 25840418, 2015). "However, SMAD4 and CD44 expression was occasionally completely lost in the invasive tumor." (PMID 26098881, 2015). "Thus, our current study supports the idea that combination therapy with c-Met inhibitor and CD44 monoclonal antibody may be more effective in anti-tumor activity than c-met inhibition alone." (PMID 25886575, 2015). "Thus, selectively targeting CD44 in tumor cells is crucially needed for this approach to work." (PMID 25909172, 2015). "In addition, CD44 depletion abrogates cancer stem cell properties of tumor initiating cells." (PMID 25605020, 2015).